SLC3A2 (solute carrier family 3 member 2)
Diseases named in the same sentence as SLC3A2 in open-access papers (continued):
Sharing a sentence is not in itself a finding about the gene and the disease.
metastatic tumor (2 papers, 2012 to 2024). "The expressions of both cystine transporters (SLC7A11, SLC3A2) and cysteine transporters (SLC1A4, SLC1A5) were significantly upregulated in CRC compared with paired non-tumor tissues, but were similar in primary tumors and metastatic tumors." (PMID 39079386, 2024).
oral squamous cell carcinoma (2 papers, 2023 to 2024). "We also detected the expression of CAV1, FTH1, and SLC3A2 in a normal oral epithelial cell line (NOK) and an oral squamous cell carcinoma epithelial cell line (HN6)." (PMID 39286654, 2024).
psoriasis (2 papers, 2023 to 2025). An autoimmune condition characterized by red, well-delineated plaques with silvery scales that are usually on the extensor surfaces and scalp. "GYS1 and SLC3A2 were highly expressed in epidermal cells from psoriatic lesions, aligning with previous reports of keratinocyte metabolic reprogramming in psoriasis." (PMID 41224720, 2025). "The identified hub genes, particularly GYS1 and SLC3A2, represent potential biomarkers and therapeutic targets, offering new insight into the complex molecular landscape of psoriasis." (PMID 41224720, 2025). "In psoriasis, SLC3A2 was enriched in epidermal cells and exhibited strong positive correlations with T follicular helper cells and CD4+ memory T cells, two immune subsets central to psoriatic inflammation." (PMID 41224720, 2025). "Venn diagram analysis revealed four overlapping genes, SLC3A2, GYS1, FLNA, and FLNB, which may serve as core candidates linking disulfidptosis to the molecular mechanisms of psoriasis." (PMID 41224720, 2025).
thymic epithelial tumor (2 papers, 2022 to 2023). "Furthermore, SLC3A2 is also an independent prognostic indicator for thymic epithelial tumors and NSCLC." (PMID 37799714, 2023).
ulcerative colitis (2 papers, 2020 to 2024). An inflammatory bowel disease involving the mucosal surface of the large intestine and rectum. "Additionally, small-molecule drug predictions have provided us with new insights into the pathogenesis of ulcerative colitis, particularly targeting the abnormal activation of the sympathetic nervous system, with SLC3A2 potentially serving as a new molecular target." (PMID 39769269, 2024).
age-related hearing-loss (1 paper, 2018). "The present work provides evidence that the amino acid transporter SLC7A8/SLC3A2 has a direct role in age-related hearing-loss (ARHL)." (PMID 29355479, 2018).
allergic rhinitis (1 paper, 2025). Inflammation of the nasal mucous membranes caused by an IgE-mediated response to external allergens. "We noted that SLC7A5 (LAT1), SLC7A8 (LAT2), and SLC3A2 (CD98), part of LAT1 and LAT2 heterodimer complexes, were significantly downregulated in allergic asthma but not in allergic rhinitis, suggesting decreased transport of Phe into the Th2 cells in more advanced allergic disease." (PMID 41308641, 2025).
bladder urothelial carcinoma (1 paper, 2024). "In addition, a group of disulfidptosis-related genes (GYS1, LRPPRC, NDUFA11, OXSM, RPN1, SLC3A2, and SLC7A1) are found to influence the prognosis of bladder urothelial carcinoma via immune cell infiltration." (PMID 39701955, 2024).
cervical cancer (1 paper, 2023). A primary or metastatic malignant neoplasm involving the cervix. "Silencing SLC3A2 inhibits mTOR pathway activity and cell proliferation in cervical cancer cells." (PMID 37940982, 2023). "In addition, SLC3A2 knockdown reduces the expression of Akt, ERK1/2 and matrix metalloproteinase (MMP) 2 and suppresses tumor progression and invasion in cervical cancer." (PMID 37940982, 2023).
childhood cancers (1 paper, 2021). "Remarkably, SLC3A2 levels are increased in both DIPG and other high-grade gliomas (HGG) with significantly higher levels than in other high-risk childhood cancers." (PMID 33579942, 2021).
choriocarcinoma (1 paper, 2023). An aggressive malignant tumor arising from trophoblastic cells. "In choriocarcinoma, vorinostat causes a decrease in the level of SLC7A11 protein through a reduction in the expression of SLC3A2, which may lead to deregulated xCT function." (PMID 36106577, 2023).
cutaneous melanoma (1 paper, 2021). A primary melanoma arising from atypical melanocytes in the skin. "For the majority of tumors assessed, significantly higher levels of SLC3A2 expression were observed in malignant vs normal tissues, most notably in colorectal, breast, genitourinary cancers and cutaneous melanomas." (PMID 34112739, 2021).
depression (1 paper, 2025). "One of the key findings of this study is that both mRNA and protein levels of GPX4, SLC3A2, and SLC7A11 were significantly downregulated in the PFC of ELS mice, and that some of these genes were specifically associated with depression-like behaviors." (PMID 41154206, 2025). "The expression levels of GPX4, SLC3A2, SLC7A11, TFR1, and lipid peroxidation markers in the PFC of mice were measured and correlated with depression-like behavioral changes." (PMID 41154206, 2025).
endothelial dysfunction (1 paper, 2025). In vascular diseases, endothelial dysfunction is a systemic pathological state of the endothelium (the inner lining of blood vessels) and can be broadly defined as an imbalance between vasodilating and vasoconstricting substances produced by (or acting on) the endothelium. "Clinically, our findings surpass previous observational associations between endothelial dysfunction and DN by proposing Slc3a2 as a functional biomarker and fludarabine as a targeted therapy." (PMID 40703306, 2025). "In conclusion, we offered a compelling narrative elucidating the indispensable role of ferroptosis and endothelial dysfunction in DN through the STAT/Slc3a2 ferroptosis signaling pathway." (PMID 40703306, 2025). "So, the comparative transcriptomics and functional assays revealed that diabetic conditions (high glucose/TNF-α) induce endothelial dysfunction via SLC3A2 suppression, triggering ferroptosis, inflammation, and fibrosis—key hallmarks of early DN." (PMID 40703306, 2025). "While our study establishes SLC3A2 downregulation and ferroptosis activation as pivotal in high glucose/TNFα-induced endothelial dysfunction, bioinformatics analysis revealed concurrent enrichment of JAK-STAT and TGF-β signaling in dysfunctional cells, suggesting multipathway cross-talk." (PMID 40703306, 2025).
Flavivirus Infections (1 paper, 2020). Infections with viruses of the genus FLAVIVIRUS, family FLAVIVIRIDAE. "Proteins differentially expressed in flavivirus infections other than Zika include SLC3A2, PODXL, ASNS and LPL." (PMID 32873194, 2020).
hepatitis C virus infection (1 paper, 2025). A viral infection caused by the hepatitis C virus. "A role for SLC3A2 had been already described for hepatitis C virus infection." (PMID 40667466, 2025).
Hypertension (1 paper, 2024). The presence of chronic increased pressure in the systemic arterial system. "The most significant SNP at the SLC3A2 (4F2hc) locus was rs2282477-T/C, with carriers of the C-allele having a lower chance to develop hypertension among CKD affected individuals [OR = 0.33 (CI 0.14–0.82); p = 0.016]." (PMID 38890684, 2024). "It is difficult, however, to establish a clear correlation between dopamine levels, LAT2/4F2hc expression, and the risk of hypertension in the context of CKD, even in view of the pleiotropic effects that dopamine and the SLC7A8/SLC3A2 genes exert." (PMID 38890684, 2024). "We examined the plausibility that SLC7A8/SLC3A2 gene polymorphisms may contribute to hypertensive CKD by affecting the L-DOPA uptake." (PMID 38890684, 2024). "The association between SLC3A2 and SLC7A8 variants to hypertension development in patients with renal failure could be linked to changes in L-DOPA uptake and consequently dopamine synthesis." (PMID 38890684, 2024). "However, to our knowledge, no studies to date have examined the effect of genetic variants of SLC7A8 and SLC3A2 genes on the relationship between CKD and hypertension." (PMID 38890684, 2024). "In conclusion, our preliminary findings derived from a hypothesis-driven candidate gene study offers suggestive evidence to support the role of SLC3A2 /SLC7A8 function to the development of hypertension in patients with renal failure." (PMID 38890684, 2024). "For rs2282477 in SLC3A2/4F2hc we also found association in a dominant model when comparing group G3 to group G4, that is the comparison between CKD subjects without versus those with hypertension, [OR = 0.33 (CI 0.14–0.82); p = 0.016]." (PMID 38890684, 2024).
laryngeal tumor (1 paper, 2022). "Since ferroptosis can be negatively regulated by SLC3A2/mTOR axis, our results suggest that targeting SLC3A2 may be an underlying approach for laryngeal tumor therapy." (PMID 35057861, 2022).
liver failure (1 paper, 2022). A liver disease characterized by the liver losing or has lost all of its function. "In summary, our research confirmed through animal experiments that ferroptosis-related genes Hmox1, Slc3a2, Jun and Zfp36 were significantly correlated with and highly expressed in liver failure." (PMID 35923893, 2022). "Finally, it was confirmed by the construction of septic liver failure mice model that ferroptosis-related genes of Hmox1, Slc3a2, Jun and Zfp36 were significantly correlated with liver failure and were highly expressed." (PMID 35923893, 2022). "Seven differentially expressed ferroptosis-related genes (Hmox1, Epas1, Sirt1, Slc3a2, Jun, Plin2 and Zfp36) were obtained through the intersection of ferroptosis-related genes in the FerrDb database with DEGs in the GSE60088 dataset, and all of these genes were up-regulated in liver failure." (PMID 35923893, 2022).
lymph node metastasis (1 paper, 2017). "SLC3A2 was significantly positively associated with serosal invasion (p = 0.002), and marginally associated with lymph node metastasis (p = 0.094, lymph node metastasis positive rate: 76.0% in low SLC3A2 group VS 86.7% in high SLC3A2 group)." (PMID 29179459, 2017).
nasopharyngeal carcinoma (1 paper, 2025). A carcinoma arising from the nasopharyngeal epithelium. "Initially, we examined SLC3A2 expression in TME-associated cells using two nasopharyngeal carcinoma datasets (GSE150430 and GSE162025) from the TISCH database." (PMID 39926285, 2025). "GEO database analysis confirmed SLC3A2's prognostic impact on nasopharyngeal carcinoma." (PMID 39926285, 2025). "Taken together, these results suggest that SLC3A2 may enhance the metabolism of tumor cells, thereby affecting the function of cytokines and the infiltration of immune cells into nasopharyngeal carcinoma tissues, and ultimately promote the progression of tumor." (PMID 39926285, 2025).
Nicotine addiction (1 paper, 2024). "Regarding KEGG pathway enrichment, the low expression group of SLC3A2 exhibited significant enrichment in Serotonergic synapse, GABAergic synapse, Neuroactive ligand-receptor interaction, and Nicotine addiction." (PMID 38977800, 2024).
Obesity (1 paper, 2022). Accumulation of substantial excess body fat. "Spearman correlation analysis results confirmed that low expression of SLC3A2 was significantly associated with Body Mass Index (BMI, p = 0.01), obesity gradation (p = 0.007), and K-L grade (p < 0.001)." (PMID 36359826, 2022). "Nonetheless, the expression of SLC3A2 was significantly negatively correlated with BMI and obesity grade." (PMID 36359826, 2022). "Spearman correlation analysis showed that the expression level of SLC3A2 in the OA cartilage-damaged area was closely related to BMI, obesity grade, and Kellgren-Lawrence grade." (PMID 36359826, 2022).
Pain (1 paper, 2025). An unpleasant sensory and emotional experience associated with actual or potential tissue damage, or described in terms of such damage. "Although no direct literature evidence supports its association with SCI, research has also revealed dysregulation of Slc7a5 and its binding partner Slc3a2 in chronic neuropathic pain conditions where they can serve as potential therapeutic targets." (PMID 39951434, 2025).
peripheral T-cell lymphoma (1 paper, 2025). "Moreover, the SSRP1/SLC3A2 axis in arginine transport represents a novel therapeutic target to counteract immune evasion and tumor progression in peripheral T-cell lymphoma." (PMID 41208974, 2025).
prostate adenocarcinoma (1 paper, 2022). "(H) Correlation of expression of 4F2 (SLC3A2) and a GCN2-dependent gene signature in prostate adenocarcinoma (PRAD, N = 551) from the Cancer Genome Atlas (TCGA)." (PMID 36107759, 2022).
rectal cancer (1 paper, 2025). A primary or metastatic malignant neoplasm that affects the rectum. "Several recent studies have confirmed that YTHDF2 can inhibit the expression of SLC7A11 and SLC3A2 through m6A modification, which in turn regulates ferroptosis in rectal cancer cells." (PMID 40948766, 2025).
renal tumors (1 paper, 2017). "Specifically, the transcript expressions of AKR1C1, S100A2, PLAU, SLC3A2, TBC1D2, and WIZ were decreased, while expressions of TGM2, SLC7A5, and NMI were increased in renal tumors when compared with non-tumorous control samples." (PMID 29272308, 2017).
spontaneous abortion (1 paper, 2024). Expulsion of the product of FERTILIZATION before completing the term of GESTATION and without deliberate interference. "Further, we found excessive uterine senescence, SLC3A2-mediated BCAA intake, and insufficient TNFRSF14 expression in the decidua of patients with recurrent spontaneous abortion." (PMID 39261664, 2024).
Stroke (1 paper, 2023). Sudden impairment of blood flow to a part of the brain due to occlusion or rupture of an artery to the brain. "In conclusion, HMOX1, TFR1 and SLC3A2 act as potential biomarkers of a stroke and play an important role in the underlying mechanism of stroke through the activation of ferroptosis." (PMID 37894877, 2023). "Iristectorin B may act as a protective agent against stroke by regulating ferroptosis, and SLC3A2, TFR1 and HMOX1 may serve as potential diagnostic biomarkers for stroke, providing additional evidence to support the importance of ferroptosis in stroke." (PMID 37894877, 2023). "Among the proteins that differ significantly in terms of their regulation of stroke through ferroptosis are TFR1, HMOX1 and SLC3A2." (PMID 37894877, 2023).
synovitis (1 paper, 2024). Inflammation of a synovial membrane. "In a lipopolysaccharide-induced synovitis model in one report, an increase in iron content and TFRC, as well as a decrease in GPX4, SLC7A11 and SLC3A2, was described, leading to increased cell death." (PMID 39513899, 2024).
tongue squamous cell carcinoma (1 paper, 2023). A squamous cell carcinoma that arises from the tongue. "Our study revealed that the genes SLC3A2 and SLC7A11, which are associated with disulphide death, are enriched in tongue squamous cell carcinoma (TSCC)." (PMID 37927242, 2023).
Usher syndrome (1 paper, 2025). A syndromic diseae characterized by the association of sensorineural deafness (usually congenital) with retinitis pigmentosa and progressive vision loss. "Several genes, such as IGHV1-69D, CTSH, and LMO7, exhibited significant upregulation in Usher syndrome, while others, including SLC3A2, ABLIM1, and CBS, were notably downregulated." (PMID 40723835, 2025).
ZIKV infection (1 paper, 2020). "Proteins previously identified to be differentially expressed during ZIKV infection include GAP43, DCX, PTPRZ1, ASNS, SLC3A2 and MKI67." (PMID 32873194, 2020).
tumor (245 papers, 2006 to 2026). "In patients with cancer, reduced expression of SLC3A2/SLC7A11 in tumor tissues is associated with a “T-cell inflamed” phenotype." (PMID 40693608, 2025). "Given that ATF4 has been implicated in regulating SLC7A11 and SLC3A2 expression in both tumor and immune cells, we focused on ATF4 for further mechanistic studies." (PMID 41042068, 2025). "SLC3A2 influences the tumour microenvironment by promoting the polarization of tumour-associated macrophages (TAMs) toward the M2 phenotype, which supports tumour growth." (PMID 41154605, 2025). "Studies have found that interfering with SLC3A2 can inhibit the M2 polarization of BLCA tumor-associated macrophages, thereby inhibiting BLCA cell proliferation, invasion, and migration." (PMID 39659999, 2024). "Elevated SLC3A2 levels have been associated with enhanced tumor growth, resistance to apoptosis, and altered metabolic states." (PMID 38977800, 2024). "It has been found that the expression of SLC3A2 is positively associated with increased disulphide bond formation between tumour cells, promoting their invasiveness and metastatic ability." (PMID 37927242, 2023). "The alterations in SLC3A2 gene had a significant correlation to relapse free survival and contributed a significant impact on BC tumor mutational burden." (PMID 37484811, 2023). "Although SLC3A2 had little change compared with common mutated genes in TCGA database, it contributed a significant impact on BC tumor mutational burden." (PMID 37484811, 2023). "In particular, the reduced expression of genes, which encode for Xc system proteins, such as SLC7A11 and SLC3A2 causes the increase in ROS-mediated lipid peroxidation and subsequent ferroptosis, even in tumor cells that are more resistant to drug treatments." (PMID 38139106, 2023). "Our results also indicated that SLC3A2 was associated with tumor infiltration of cytotoxic T cell among BC TME." (PMID 37484811, 2023). "It has previously been shown that upregulation of SLC3A2 in tumor biopsies was associated with poor survival of OSCC patients." (PMID 38069306, 2023). "Tumor survival, migration, proliferation, and sensitivity to radiotherapy are regulated by SLC3A2, and its high expression is associated with poor prognosis." (PMID 37404825, 2023). "Studies have also shown a close association between SLC3A2 expression and clinical malignant features such as tumour invasion, metastasis and drug resistance." (PMID 37927242, 2023). "Serum SLC3A2 protein was associated with tumor differentiation, lymphatic invasion, and venous invasion in both LUAD and LUSC patients (p < 0.05)." (PMID 36358610, 2022). "In this study, we confirmed that serum SLC3A2 is associated with tumor differentiation, lymphatic invasion, and venous invasion in both LUAD and LUSC patients." (PMID 36358610, 2022). "Future studies are encouraged to explore the underlying mechanism by which SLC3A2 affects anti-tumor immunity." (PMID 35992269, 2022). "Our results indicated that high co-expression of the SLC7A5/SLC3A2 complex is associated with poor prognostic clinicopathological parameters, including a larger tumour size, higher grade, poor NPI and vascular invasion." (PMID 32093034, 2020). "Quantitative determination of human Alu expression in chick embryo lungs by qRT-PCR also showed that intravasated tumor cells were significantly decreased to 15.9% in SLC3A2 deficiency group." (PMID 29179459, 2017). "In addition, SLC3A2 levels were positively associated with arginine metabolism pathway scores in Tfh tumor cells." (PMID 40344476, 2025). "In a study, it was found that SLC3A2 is expressed in a broad range of human cancers but its expression in normal tissues is restricted to the kidney, testis, and cerebellum, making this protein a tumor-associated antigen." (PMID 38705513, 2024).